DUX4L35 (double homeobox 4 like 35 (pseudogene))
Gene: Unprocessed pseudogene on chromosome 20 (29,448,517 to 29,449,306, reverse strand). Ensembl gene ENSG00000282911.
Diseases named in the same sentence as DUX4L35 in open-access papers:
DUX4L35 is named in the same sentence as 1 disease in open-access papers, as found by Europe PMC text mining. Sharing a sentence is not in itself a finding about the gene and the disease.
DUX4L35 shares sentences with these, for which no sentence is quoted: Skeletal muscle atrophy (1 paper).